DEFB108A (defensin beta 108A)
Description:
Has antibacterial activity.
Synonyms: DEFB-8; formerly DEFB108; DEFB108P1
Gene: Unprocessed pseudogene on chromosome 8 (7,934,412 to 7,938,770, reverse strand). Ensembl gene ENSG00000229907.
Subcellular location: Secreted